ENSG00000270823 (novel transcript, antisense to MEST)
Gene: Long non-coding RNA gene on chromosome 7 (130,495,794 to 130,498,427, reverse strand). Ensembl gene ENSG00000270823.
Gene Ontology:
Biological process: miRNA-mediated post-transcriptional gene silencing
Cellular component: RISC complex